ALB (albumin)
Diseases named in the same sentence as ALB in open-access papers (continued):
Sharing a sentence is not in itself a finding about the gene and the disease.
pancreatic cancer (continued). "Other research encompassed the analysis of various medical conditions beyond pancreatic cancer, and no disparities were identified between elderly and non-elderly patients in terms of nutritional and immune markers, except for albumin levels." (PMID 38592055, 2024). "This study was designed to compare various blood biomarkers, such as neutrophil/lymphocyte ratio (NLR), lymphocyte/monocyte ratio (LMR), platelet/lymphocyte ratio (PLR), C-reactive protein (CRP), albumin (Alb), plasma fibrinogen (PF), and CRP/Alb in patients with pancreatic carcinoma." (PMID 38496751, 2024). "Through these receptors, albumin nanoparticles are internalised to the tumour interstitium, where they bind to secreted acidic proteins rich in cysteine (SPARC) that are overexpressed in many tumours, such as lung, breast, and pancreatic carcinomas." (PMID 39771562, 2024). "Recent studies have shown the efficacy of a combination therapy in a mouse model of pancreatic cancer, where thermally responsive elastin-like polypeptide (ELP) conjugated with iodine-131 radionuclides (131I-ELP) were delivered through nanoparticle albumin-bound paclitaxel." (PMID 38259846, 2023). "Albumin nanoparticles such as nanoparticle albumin-bound paclitaxel (nab-paclitaxel) are widely used as monotherapy or combination therapy of metastatic breast cancer, non-small-cell lung cancer (NSCLC) and advanced pancreatic cancer (PC)." (PMID 36839841, 2023). "A paclitaxel (PTX)-bound albumin nanoparticles with embedded TRAIL (TRAIL/PTX HSA-NP) formulation based on paclitaxel-bound albumin nanoparticles embedded with TRAIL showed improved TRAIL efficacy both in vitro and in vivo pancreatic cancer models." (PMID 36496977, 2022). "Consistent with previous reports regarding native albumin, transient KRASG12D overexpression in KRAS wt BxPC-3 cells and inducible KRASG12D expression in tumor cells derived from a genetically engineered mouse model of pancreatic cancer, both enhanced nab-PTX uptake by ≥8-fold." (PMID 35154489, 2022). "Importantly, pancreatic cancer cells, but not adjacent, non-tumor pancreatic tissue cells, rely on macropinocytosis and albumin catabolism in vivo." (PMID 33401771, 2021). "However, to date, the prognostic value of pretreatment bilirubin and ALB in advanced pancreatic cancer has not been fully explored." (PMID 30474926, 2018). "The dependent variable was the presence or absence of NLR < 5 at 4 weeks, while explanatory variables included the presence or absence of pancreatic cancer, baseline NLR < 4.4, albumin level, and lymphocyte count." (PMID 39981448, 2025). "The number of pancreatic cancer patients who received chemotherapy with and without diarrhea were 4 cases (Gemcitabine (GEM) plus S− 1 [2cases], S-1 [2cases]) and 3 cases (GEM, nanoparticle albumin-bound paclitaxel plus GEM, FOLFIRINOX), respectively." (PMID 33517900, 2021).
Cachexia (211 papers, 2008 to 2026). Severe weight loss, wasting of muscle, loss of appetite, and general debility related to a chronic disease. "One possibility is that SMD decreases due to cancer-related cachexia, a condition linked to factors such as low albumin levels and increased clearance of anti-PD1 antibodies." (PMID 39980388, 2025). "Second, serum albumin is widely considered a marker of immune and nutritional status, with low albumin levels linked to poorer postoperative outcomes and cachexia in patients with cancer." (PMID 40678069, 2025). "Due to limited availability of inflammatory markers, such as CRP or ratios derived from a CBC with differential, we were unable to assess levels of systemic inflammation, a hallmark of cancer‐associated cachexia, between groups beyond serum albumin levels." (PMID 38123146, 2024). "TNF-α, a cytokine known as a mediator of inflammation and tumor-associated cachexia, controls the concentration of ALB." (PMID 37505298, 2024). "Albumin and to a lesser degree low BMI have been recognized as markers of tumor-associated cachexia." (PMID 39414641, 2024). "Next, we investigated the effect of a given nutritional combination on the parameters of cachexia diagnostic items, typically including losses of weight, lean body and fat mass, and abnormalities in levels of albumin." (PMID 39273055, 2024). "Wasting syndromes exhibit maladaptive reactions, such as loss of appetite and increased metabolism, which can lead to low serum albumin levels, weight loss, decreased muscle mass, and, intriguingly, the preservation or even an increase in fat mass." (PMID 38276262, 2023). "Subjects with less than 5% body weight loss (3.78 ± 0.555 g/dl, p = 0.0364) and cachexia (3.79 ± 0.459 g/dl, p = 0.0325) had lower serum albumin than controls (4.11 ± 0.597 g/dl)." (PMID 34791809, 2022). "In contrast, only ALP and the cachexia‐related markers haemoglobin and albumin were associated with late mortality after adjustment for age and sex." (PMID 35257497, 2022). "Of interest, markers of cachexia such as low albumin and haemoglobin were also associated with late mortality independent of age and sex." (PMID 35257497, 2022). "The underlying inflammation in cachexia is recognized not only by higher levels of C-reactive protein (CRP) or low albumin, but a plethora of inflammatory proteins appears also to be altered in this syndrome." (PMID 35174197, 2021). "In the analyzed papers, patients’ nutritional status was evaluated using questionnaires (MNA or SGA), or measures such as BMI, weight loss (WL), albumin levels, and anorexia or cachexia." (PMID 34684333, 2021). "TNF-ɑ inhibited albumin expression in a murine model of cachexia even before the onset of weight loss." (PMID 34001060, 2021). "As such, albumin is considered a biomarker of cachexia, a state characterised by weight loss, systemic inflammation and reduced functional status and associated with poor prognosis in many diseases." (PMID 34660664, 2021). "In other words, 60% of BC patients exhibiting a rate of weight loss consistent with cachexia had normal serum albumin, while BC patients with serum albumin <3.4 g dL−1 only had a 17.3% chance of exhibiting a rate of weight change consistent with cachexia." (PMID 32550263, 2020). "Yet, routine laboratory parameters, such as C-reactive protein, hemoglobin, albumin and cholinesterase, have also been implicated in patients with cachexia." (PMID 31717736, 2019). "Concerning these parameters, an increase in CRP and reductions in hemoglobin and albumin as well as CHE were previously linked to cachexia." (PMID 31717736, 2019). "While there are no specific laboratory markers for cachexia, it is commonly agreed that inflammatory parameters, including leukocyte count, CRP, and CHE as well as hemoglobin and albumin are associated with cachexia." (PMID 31717736, 2019).
Cachexia (continued). "Pre-operative serum albumin levels were significantly lower in these patients with gastric outlet obstruction reflecting the nutritional deficit and the development of a cachexia associated with cancer." (PMID 30972486, 2019). "This process is likely influenced by cachexia, as a considerable amount of Ca2+ in the blood associates with albumin." (PMID 28417928, 2017). "This cachexia model involves significant anorexia, weight loss, body composition changes, increased inflammatory marker levels, and low serum albumin levels, fulfilling the cachexia diagnostic criteria." (PMID 25540621, 2014). "The patients had high CRP and IL-6 levels and low serum albumin levels, which are part of the suggested diagnostic criteria for cachexia, acknowledging that CRP and IL-6 mainly are markers of inflammation." (PMID 21483870, 2011). "Our cachexia patients had unambiguous signs of cachexia, including self-reported unintentional weight loss, low serum albumin and impaired nutritional status (SGA)." (PMID 20407445, 2010). "Therefore, cachexia is closely associated with unfavorable prognostic variables found in the current study, including high PS, low albumin level, high CRP, and low BMI." (PMID 38438534, 2024). "In hospitalised cachexia patients, lymphocytes and albumin levels are linked." (PMID 39130833, 2024). "Low serum albumin concentrations and BMI are also independent factors associated with cachexia." (PMID 39272892, 2024). "This could be of importance in patients with cachexia, as low serum albumin levels are associated with a low nutritional status and thus cachexia, and larger studies on the correlation between low serum albumin levels and the efficacy of ICI are warranted." (PMID 38201657, 2024). "First, a substantial tumor burden may be associated with cachexia 46 and decreased serum ALB levels 47, resulting in a lower AGR." (PMID 36741261, 2023). "Patients who received previous treatment might have poor nutritional status due to cachexia caused by disease progression or low albumin values which have been occasionally observed as adverse events of TKIs." (PMID 37968545, 2023). "Low serum albumin is one of the components in diagnostic criteria for cachexia." (PMID 37352293, 2023). "The reduction of albumin metabolic reserve due to age may often cause patients to fail to cope with the systemic inflammatory pressure caused by cachexia." (PMID 34585849, 2021). "Therefore, ALB, which is a readily detectable biomarker of cachexia, was combined with BMI to evaluate its association with OS." (PMID 34414685, 2021). "In addition, serum albumin, which is associated with cachexia and mortality, was similar between our RMC and matched controls and when adjusted for, did not impact the association between SM and RMC diagnosis." (PMID 34885132, 2021). "If patients are malnourished, defined as albumin <3.5 g/dL, significant weight loss, and cachexia, then 1–3 months of EEN or TPN may improve surgical outcomes." (PMID 32635316, 2020). "In contrast, albumin in T mice was significantly lower than that in mice treated with TNuF or the combination, concluding that TNuF effectively alleviates cancer-associated cachexia." (PMID 31426614, 2019). "Plasma albumin may decrease only at advanced stages of AN-related cachexia, usually during phases of rapid worsening of weight loss with added complications such as pulmonary infections, diarrhea or profound pressure ulcers." (PMID 28257095, 2017). "Cancer cachexia is defined as >5% weight loss, which is closely associated with muscle weakness, fatigue, anorexia, low lean body mass and certain abnormal physiological symptoms, such as inflammation, anemia, low serum albumin." (PMID 25797259, 2015).
Cachexia (continued). "In CKD, a wasting or cachectic syndrome is observed, and while the mechanisms behind cachexia are intricate, they encompass factors such as anorexia, nausea, vomiting, increased basal metabolic rate, loss of lean body mass, and reductions in serum proteins like albumin, transferrin, and prealbumin." (PMID 38276262, 2023). "Furthermore, individuals with decreased levels of serum albumin and total protein, as well as lower hemoglobin A1c and BMI may be at risk of developing cachexia, a common condition among patients with COPD." (PMID 34255684, 2021). "Indeed, Zn2+ availability in cancer patients could be reduced because albumin, a major vehicle of plasma Zn2+, is decreased in association with cachexia." (PMID 28417928, 2017). "The cachexia index was calculated as: (psoas muscle index × albumin level [g/dL]/neutrophil-to-lymphocyte ratio)." (PMID 41799593, 2025). "To investigate these parameters, we isolated serum from a CT26-induced cancer cachexia mouse model to measure the levels of CK, albumin, TG, cholesterol, HDL, LDL, and pro-inflammatory cytokines." (PMID 40469669, 2025). "Based on these findings, it can be concluded that myosteatosis and serum albumin levels reflect cachexia in different ways." (PMID 41002580, 2025). "Consistent with prior research linking elevated serum IL-6 to cachexia, our findings also indicate that subjects with decreased albumin levels present with significantly elevated IL-6 concentrations." (PMID 38672257, 2024). "Recently, the cachexia index (CXI), which was calculated from the skeletal muscle mass index (SMI), serum albumin concentration, and neutrophil-to-lymphocyte ratio, was developed to evaluate cancer cachexia." (PMID 39468284, 2024). "Previously published studies have shown that albumin and NLR levels are associated with the prognosis of cachexia." (PMID 38775250, 2024). "In multivariate Cox analysis, we found that the risks of reduced long-term survival in cancer cachexia patients with low albumin, prealbumin and transferrin levels were 1.51, 1.42, and 1.50 times higher than those with high hepatic protein levels." (PMID 38438901, 2024). "In the investigation of relationships of QoL to biomarkers of cachexia, the results showed that albumin, NLR, Hb, PLR, SII, TNFα, IL-8, and CRP were all significantly related to QL-G, QL-FS, and QL-SS aspects of QoL assessment." (PMID 38744744, 2024). "The risks of 90-days mortality and impaired QoL were higher in cachexia patients with low albumin, prealbumin, and transferrin levels." (PMID 38438901, 2024). "A low albumin level is an independent unfavorable factor for cachexia patients with upper gastrointestinal, hepatobiliary and pancreatic and colorectal cancers." (PMID 38438901, 2024). "The median OS and PFS of cachexia patients with both low serum albumin levels and high serum CRP levels were 6.0 months and 0.93 months, respectively." (PMID 38592548, 2024). "NLR, PLR, SII, TNFα, IL-6, IL-8, and CRP correlated positively to cachexia and albumin while Hb and lymphocyte count correlated negatively to cachexia." (PMID 38744744, 2024). "Intramuscular injections of TNFα, induced cachexia and coincided with decreased hepatic albumin synthesis." (PMID 38022578, 2023). "The significantly lower albumin value of the patients versus that of the controls’, is suggestive of the advanced nature of the cachexia in this study." (PMID 37906352, 2023). "Regarding biomarkers, cachexia was associated with higher CRP, blood urea nitrogen and BNP and lower albumin, haemoglobin and haematocrit levels." (PMID 37434419, 2023). "In contrast, mGPS can predict the prognosis and evaluate the progression of cachexia based on CRP and albumin levels, which can classify cachexia stages." (PMID 37686634, 2023). "Patients with low albumin levels, a sign of poor nutritional status, are prone to experiencing cachexia or infection." (PMID 37576904, 2023).
Cachexia (continued). "In subjects with cachexia, vaccenic remained strongly negatively correlated with albumin (r= −0.646, p = 0.005), whereas linoleic was positively correlated with albumin (r = 0.577, p = 0.015)." (PMID 35269531, 2022). "Univariate analysis revealed cachexia, tumor at the tongue/floor of the mouth (TFOM), T4 stage, preoperative hemoglobin level, pull-through procedure, preoperative albumin level, and surgical site infection were associated with the formation of OCF." (PMID 35558508, 2022). "Levels of hemoglobin and albumin are typically lower in patients with cachexia, and these clinical factors are used in some definitions of cachexia." (PMID 35269531, 2022). "CXI is a new measure of cachexia that is calculated as SMI (cm2/m2) × serum albumin (g/L)/NLR, and these three parameters are objective and easily accessed from abdominal CT scans, routine peripheral blood, and biochemical tests." (PMID 36212479, 2022). "It is also an indicator of cachexia since liver albumin production is inhibited by malignancy and inflammation." (PMID 36661543, 2022). "Although it was not identified as a potential confounder, we performed a sensitivity analysis where albumin, a surrogate for cachexia, was included as a covariate in our multivariable model for SM, and SM remained significantly associated with RMC diagnosis." (PMID 34885132, 2021). "We evaluated the albumin levels obtained at the time of diagnosis as a surrogate measure of cachexia." (PMID 34885132, 2021). "The cachexia index (CXI) was calculated as skeletal muscle index × serum albumin level (g/dL)/neutrophil-to-lymphocyte ratio." (PMID 34001060, 2021). "Albumin, like other biomarkers of systemic inflammation, reflects the multi-factorial syndrome of cachexia." (PMID 34660664, 2021). "Following literature data, here, we found a diminished carcass weight added to a reduction in serum albumin and total protein levels, features related to the cachexia process." (PMID 34940589, 2021). "Similar results were derived from multivariable regression analysis, and the patients with low albumin levels had over a sevenfold greater chance of developing cachexia (OR = 7.69; p = 0.005)." (PMID 33807923, 2021). "We also found that the low level of albumin among patients with CHF resulted in a sevenfold greater chance of developing cachexia (OR = 7.69; p = 0.005)." (PMID 33807923, 2021). "The univariate analysis revealed a low concentration of albumin (mean <3.20 g/dL; OR = 13.6; p < 0.001) as the most significant factor affecting cachexia in CHF patients." (PMID 33807923, 2021). "In the present study, high SII correlated with low albumin levels, suggesting that cachexia had an influence on the results obtained." (PMID 34118953, 2021). "A high dose of n-3 offered for 8 weeks was able to increase albumin and improve body weight in the patients with severe cachexia." (PMID 35174197, 2021). "Patients without COPD who took beta-blockers presented with younger age, higher BMI, lower prevalence of NYHA classification at discharge ≥III and cachexia, higher albumin, and higher prevalence of RAS inhibitors compared to those who did not." (PMID 34640396, 2021). "Patients with cachexia were characterized by significantly lower weight, body mass index (BMI), lower fat mass (FM), albumin, and hemoglobin." (PMID 34635743, 2021). "Accordingly, increased levels of inflammatory cytokines in tumors increase the demand for amino acids, resulting in the decreased serum albumin levels of patients with cachexia." (PMID 32982584, 2020). "The univariate analysis revealed albumin concentration and Cm value as the factors, that most significantly affect probability of cachexia in CHF patients (OR = 33.18 and OR = 10.76, respectively)." (PMID 32260434, 2020). "Several markers for malnutrition and cachexia such as body mass index (BMI), sarcopenia, adipopenia, and serum albumin level have been studied and suggested to be prognostic factors in DLBCL." (PMID 32423395, 2020).